CPT1A (carnitine palmitoyltransferase 1A)
Diseases named in the same sentence as CPT1A in open-access papers (continued):
Sharing a sentence is not in itself a finding about the gene and the disease.
tumor (continued). "To examine the effect of silencing CPT1A on tumor growth in vivo, we subcutaneously injected control and CPT1A knockdown SW480 cells mixed with Matrigel alone or in combination with human adipocytes into NSG mice and monitor the tumorigenesis process." (PMID 32913185, 2020). "GSEA analysis demonstrated that CPT1A modulates tumor development via a variety of biological pathways in KIRC." (PMID 33381539, 2020). "To confirm the involvement of PPARδ in regulating CPT1A, we showed that treating PT130 cells or Apc/Kras tumor organoids with PPARδ agonist GW501516 directly stimulated the expression of CPT1A and PPARGC1A (a known PPARδ target gene)." (PMID 32913185, 2020). "First, the Apc/Kras tumor organoids were embedded with adipocytes in 3D Matrigel or treated with different fatty acids and the expression of Cpt1A was monitored using Western blot and RT-PCR analysis." (PMID 32913185, 2020). "We believe that CPT1A most likely suppresses tumor progression by employing tumor “slimming” in KIRC." (PMID 33381539, 2020). "Taken together, our results suggest that CPT1A is required for adipocytes to enhance the tumor initiation potential in vivo." (PMID 32913185, 2020). "Although we show that inhibition of FAO is coupled with decreased cell survival and β-catenin activation in CPT1A knockdown cells, it is possible that CPT1A mediates the tumor promoting effects of adipocytes using a FAO-independent mechanism." (PMID 32913185, 2020). "Among metabolic markers, the expressions of FASN and CPT1A were characterised by higher H-scores in tumour cells (median H-score = 210 and 240, respectively), in contrast to those in normal breast epithelium (respectively)." (PMID 32899149, 2020). "In the KIRC dataset of the TCGA database, we observed that CPT1A expression is related to the tumor, metastasis, grade, and stage of patients with RCC." (PMID 33381539, 2020). "This study provides new knowledge of the role of lipid catabolism in the intercommunication of tumor and immune cells, which can be extrapolated to other cancers with high CPT1A expression." (PMID 33352903, 2020). "Analysis of tumor tissues collected from four groups of mice revealed that knockdown of CPT1A decreased the amount of active β-catenin, although we did not observe the adipocyte-induced activation of β-catenin in tumors derived from control cells." (PMID 32913185, 2020). "Silencing CPT1A abolished the protective effect provided by fatty acids against nutrient deprivation and reduced tumor organoid formation in 3D culture and the expression of genes associated with cancer stem cells downstream of Wnt/β-catenin." (PMID 32913185, 2020). "Only one difference was detected between the in vitro and in vivo data—CPT1A expression was increased in the case of doxorubicin-treated MDA-MB231 tumours in vivo." (PMID 32899149, 2020). "Further analysis of TMA revealed that tumor epithelial cells adjacent to COL11A1-postive stroma showed the strongest CPT1A expression." (PMID 32312965, 2020). "Collectively, our results suggest that fatty acid treatment enhances Wnt signaling in tumor organoids using a CPT1A-dependent mechanism." (PMID 32913185, 2020). "Here, we observed, for the first time, that the low expression level of CPT1A in KIRC patients is associated with poor overall survival rate, larger tumor size, and higher tumor grade." (PMID 33381539, 2020). "Similar decrease in the levels of active β-catenin and acetylated α-tubulin, H3K9 and H3K27 was observed in Cpt1a knockdown tumor organoids." (PMID 32913185, 2020). "Regarding the C4-2 and 22RV1 CPT1A OE cells, both tumor models showed increased growth compared with controls (respectively)." (PMID 31547059, 2019). "Since the relevance of increased CPT1A expression in advanced PCa is emerging, in this study, we investigated the role of CPT1A in castration-resistant cell and tumor models." (PMID 31547059, 2019).
tumor (continued). "Expression of CPT1A – the gene encoding the enzyme catalysing the rate-limiting step in FAO – was lower in ER-negative, compared to ER-positive tumours in most of the datasets analysed." (PMID 30092766, 2018). "Functionally, repression of CPT1A is critical for tumor formation, as elevated CPT1A expression limits tumor growth." (PMID 29176561, 2017). "In contrast, one tumor that was harvested at the size of 60 mm3 was stained for CPT1A expression by immunofluorescence and with Oil Red O for lipid droplet detection revealed abundant CPT1A and sparse lipid deposition compared to a control tumor." (PMID 29176561, 2017). "The importance of CPT1A repression was determined in re-expression studies, in which we observed an inhibition of lipid deposition and a correlated inhibition of tumor growth." (PMID 29176561, 2017). "CPT1A restoration led to significant decreases in tumor growth, as assessed by two-way ANOVA (p = 0.0034)." (PMID 29176561, 2017). "Despite decreased expression in the cytoplasm of several tumor tissues, CPT1A expression was found to localize in the nuclei, where it interacts with histone deacetylase protein complexes in neoplastic cells." (PMID 22533991, 2012). "Importantly, targeting CPT1A can enhance immune checkpoint blockade-induced anti-tumor immunity and augment tumoral ferroptosis in tumor-bearing mice." (PMID 41601687, 2026). "Targeting CPT1A could inhibit tumor cell proliferation, suggesting that this pathway may serve as a potential therapeutic target for TFE3 rRCC." (PMID 41716419, 2026). "This TFE3/PGC-1α/CPT1A axis enhanced tumor cell proliferation, migration, and invasion." (PMID 41716419, 2026). "In vivo, targeting CPT1A markedly suppressed tumor growth and restored cisplatin sensitivity." (PMID 42209453, 2026). "However, treatment with the CPT1A inhibitor Etomoxir suppressed tumor growth, consistent with the in vitro findings." (PMID 41310903, 2025). "Additionally, the upregulation of LPL, FATP2, and CPT1A, which are essential enzymes involved in FA metabolism, is directly correlated with tumor aggressiveness and lymph node metastases, making these viable biomarkers for PTC prognosis." (PMID 41041104, 2025). "Continuous CPT1A transcription is jointly regulated by cancer-type organic anion transporting polypeptide 1B3 and insulin-like growth factor 2 mRNA-binding protein 2, and its function is related to lamellipodia formation in tumor cells." (PMID 41219902, 2025). "Furthermore, after treatment, dormant tumor cells presented increased β-oxidation, elevated ATP levels, and upregulated CPT1A expression, collectively indicating that increased energy demand serves as the primary driver of their reactivation from dormancy." (PMID 41214328, 2025). "Additionally, macrophage-mediated phagocytosis of tumour cells increased when tumour cells were pretreated with PDC-E2 or CPT1A inhibitors." (PMID 41163221, 2025). "In addition, CPT1A is significantly upregulated in GC tissues, which correlates with enhanced tumour proliferation, invasion, and EMT." (PMID 41154605, 2025). "At the same time, there are many drugs with unknown targets that may modulate FAO, such as high-dose dexamethasone, which can delay tumor growth and promote apoptosis by inhibiting CPT1A,164 and metformin, which also inhibits FAO in breast cancer." (PMID 40290117, 2025). "Additionally, CPT1A (Carnitine Palmitoyltransferase 1A)-mediated fatty acid oxidation alters T-cell metabolism, leading to T-cell exhaustion and impaired anti-tumor responses." (PMID 40076502, 2025). "While such anti-tumor activity was partly offset by CPT1A overexpression." (PMID 41444950, 2025). "However, in tumor tissues, an increase in CPT1A was observed after CPI‐613 treatment, which was reduced with the addition of LNP‐sgFAT1." (PMID 40407216, 2025).
tumor (continued). "Besides, sh-RACGAP1 group showed highest level of 4-HNE, a ferroptosis marker indicating cytotoxic lipid peroxidation, and highest iron content in tumor tissue than control and sh-NC groups, while such changes were partly blocked by CPT1A overexpression." (PMID 41444950, 2025). "In this study, CPT1A gene expression stimulation is mediated by removing m6A (N6-methyladenosine) modification, which is a reversible RNA epigenetic modification that regulates RNA processing, shown to take part in tumor development and progression." (PMID 40361394, 2025). "In addition, similar to OVOL2‐overexpression, knockdown of CPT1A inhibited tumor initiation in MDA‐MB‐231 xenografts in nude mice." (PMID 38627980, 2024). "Nrf2 inhibition in combination with Cpt1a ablation significantly reduced tumor cell proliferation." (PMID 39097623, 2024). "However, in contrast with non-tumour tissues, mRNA levels of Cpt1a, Acad11 and Srebp1c were downregulated in mouse HCC." (PMID 39203941, 2024). "Silencing of CPT1A exerts tumor-suppressing functions in PCa by suppressing glycolysis." (PMID 38494680, 2024). "CPT1A affects tumor cell proliferation by influencing cellular and nucleotide metabolism." (PMID 38753091, 2024). "Furthermore, tumor infiltration by IFNγ-expressing CD8 + T cells was increased in the Cpt1a ablated/7.16.4 mAb-treated tumors compared with control groups, consistent with the recruitment and activation of cytotoxic, anti-tumor leukocytes." (PMID 39097623, 2024). "It remains unclear whether CPT1A can regulate the radiosensitivity of the entire tumour microenvironment in immunocompetent mice." (PMID 39607749, 2024). "CPT1A staining was uniform throughout the tumor sections with low to moderate intensity." (PMID 37628819, 2023). "Therefore, high CPT1A expression, which potentially leads to the high absorption of those fatty acids by the tumor, will take advantage of those fatty acid mobilizations, promoting increased cancer proliferation." (PMID 36735704, 2023). "Furthermore, western blotting, cell proliferation assays and anchorage-independent growth assays showed that FDXR KD in tamoxifen- or fulvestrant-resistant T47D and MCF7 cell lines inhibited CPT1A expression and decreased tumor cell growth." (PMID 37207154, 2023). "In addition, t-tests confirmed a significant difference in CPT1A expression between the tumor-free cortex and the GBM." (PMID 36221088, 2022). "Studies in other cancer types support the role of CPT-1A as a driver of tumour progression." (PMID 36180554, 2022). "In addition, the anti-tumor mechanism of mTORC involves the reduction of CPT1A expression and lipid catabolism." (PMID 35896782, 2022). "We found that knockdown of CPT1A significantly decreased tumor growth and tumor weight in vivo." (PMID 35411000, 2022). "CPT1A overexpression in ccRCC is known to limit tumor growth." (PMID 35223522, 2022). "Down-regulated CPT1A expression reduces lipid utilization by attenuating lipid catabolism, which contributes to the downregulation of cancer-related gene expression and apoptosis of the tumor cells." (PMID 35896782, 2022). "Interestingly, we did not observe any significant difference in the expression of the proliferation marker Ki67 in CPT1A KD tumor tissues compared to vector control." (PMID 34944922, 2021). "CPT1A expression could influence the extent of hypoxic areas in the tumor as well as PCa cell proliferation in these harsh areas through the maintenance of malignant hypoxic niches." (PMID 34944922, 2021). "We hypothesized that CAFs could experience an increase in FAO by upregulating CPT1A expression to increase lipid oxidation resulting from tumor‐imposed glucose restriction." (PMID 33528867, 2021). "First, we performed WB and IHC to determine expression of CPT1A in tumour and para-tumour tissues." (PMID 34976793, 2021).
tumor (continued). "Finally, we found that directly blocking FAO in CAFsCPT1A‐OE with etomoxir inhibits migration and invasion in vitro and decreases tumor growth and intraperitoneal dissemination in vivo, revealing a role for CAF CPT1A in promoting tumor growth and invasion." (PMID 33528867, 2021). "CPT1A is a rate-limiting transporter controlling fatty acid oxidation, and its overexpression upregulates β-oxidation of fatty acids and ATP levels to facilitate tumor cell proliferation." (PMID 34638280, 2021). "Previous studies showed upregulation of CPT1A is essential for the tumor-promoting effect." (PMID 34052835, 2021). "However, more studies are warranted to assess CPT1A protein expression and activity and its colocalization with hypoxic conditions or the expression of hypoxic biomarkers in clinical tumor samples." (PMID 34944922, 2021). "Furthermore, we performed tumor initiation experiments by injecting control and CPT1A knockdown SW480 cells mixed with Matrigel alone or in combination with adipocytes into NSG mice at 100 and 1000 cells per site." (PMID 32913185, 2020). "Interestingly, the expression of CPT1A was significantly increased in tumor cells that have invaded into the omental adipose tissue (adipocyte adjacent) compared to tumor cells without direct contact with adipocytes (primary tumors)." (PMID 32913185, 2020). "Furthermore, knockdown of CPT1A blocked the tumor-promoting effect of adipocytes in vivo and inhibited xenograft tumor initiation." (PMID 32913185, 2020). "Although knockdown of CPT1A did not significantly decrease the tumor growth rate basally compared to the control group, CPT1A-loss blocked the tumor promoting effect of adipocytes in vivo." (PMID 32913185, 2020). "The study also demonstrated that CPT1A was significantly correlated with tumor radiosensitivity." (PMID 33381539, 2020). "In addition, CPT1A downregulation induces differentiation of tumor organoids grown in 3D and attenuates the effect of fatty acids on promoting the expression of cancer stem cell-associated genes." (PMID 32913185, 2020). "In addition, since the 3D growth media are enriched in fatty acids, silencing Cpt1a also reduced the rate of cell proliferation in tumor organoids." (PMID 32913185, 2020). "Importantly, CPT1A expression is required for adipocytes to promote tumor growth and initiation in vivo." (PMID 32913185, 2020). "Treatment of patients with CPT1A inhibitors could potentially re-activate the immune cells to restore and enhance cellular-mediated antitumor immunity and tumor regression." (PMID 33352903, 2020). "Interestingly, while control tumor cells formed spherical organoids in 3D, the Cpt1a knockdown organoids showed branched phenotype suggesting potential differentiation." (PMID 32913185, 2020). "Finally, we observed that in clinical samples, CPT1A expression is reduced in tumors compared to normal kidneys, and significantly that CPT1A activity is reduced in mitochondria harvested from tumor tissue compared to adjacent normal kidney tissue." (PMID 29176561, 2017). "Together, the studies indicate that CPT1A repression is recapitulated in human tumor samples, and that the level of repression may have prognostic value." (PMID 29176561, 2017). "Thus, we conclude that CPT1A expression is incompatible with ccRCC tumor growth, and that HIF-mediated suppression of CPT1A is a requisite step in ccRCC development in model systems." (PMID 29176561, 2017). "We next wanted to determine whether stable expression of CPT1A could lead to more profound effects on tumor growth, and thus turned to creating a doxycycline-inducible cell line." (PMID 29176561, 2017). "Thus, we propose nuclear CPT1A as a striking tumor specific target for anticancer therapeutics, more selective and effective as compared with the well-known HDAC inhibitors." (PMID 26799588, 2016).
tumor (continued). "In addition, CD24 has been shown to be an upstream regulator of the transcription factor PPARα and NF-κB signaling pathways, promoting tumor growth, proliferation, and stemness by upregulating the expression of CPT1A, thereby metabolically reprogramming the mitochondrial FAO pathway." (PMID 39596847, 2024). "Interestingly, CPT1A/Whd, an important regulator of the beta-oxidation pathway, was found to be upregulated both at the transcriptional (QRasV12scribRNAi) and protein levels (RasV12dlg1RNAi) in the muscles of tumour-bearing animals." (PMID 38429578, 2024). "Additionally, Etomoxir (Eto, a CPT1a inhibitor) significantly impaired the OCR (oxygen consumption rate) of parental HCT116 cells incubated with tumor-adipocyte-co-cultured supernatant, particularly in MIIP+/−-derived supernatant cultured cells but not in conventional (McCoy's 5A) cultured cells." (PMID 38245780, 2024). "The reasons for the decreased expression of CPT1A in tumour cells remain unclear." (PMID 39607749, 2024). "After 16 days of treatment with 10 mg/kg of IKE, 15 mg/kg of Eto, or both, spleen MDSCs isolated from MC38 tumor-bearing mice were identified by flow cytometry to further examine whether inhibiting CPT1A may improve IKE-induced MDSC actual ferroptotic death in vivo." (PMID 39596904, 2024). "Thus, our data indicate that FDXR regulates tumor cell growth through CPT1A." (PMID 37207154, 2023). "Therefore, targeted inhibitors of CPT1A may be a new strategy for the treatment of clinical tumours." (PMID 37416765, 2023). "In addition, tumor-infiltrating Tc9 cells expressed a higher level of CPT1A than Tc1 cells." (PMID 35192544, 2022). "In addition, CPT1a expression was increased around fat depots within the tumor, consistent with the literature, pointing out that local heterogeneity exists within the tumor." (PMID 35158830, 2022). "It is also worth mentioning that CAFs in colon cancers enhance the expression of CPT-1A to actively oxidize FAs, thus enhancing the ability of CAFs to secrete cytokines such as CCL2, VEGF-A, and MMP2 which are associated with angiogenesis and metastasis of tumor cells." (PMID 35003369, 2021). "However, it may be that the optimal functionality of CPT1A is essential for cells to survive under conditions of added stress, such as hypoxia or drug treatments, particularly in early tumor development." (PMID 34944922, 2021). "Therefore, even though we did not observe significant changes in proliferation and angiogenesis markers through IHC, CPT1A expression could regulate the maintenance of malignant hypoxic niches, thereby promoting tumor growth." (PMID 34944922, 2021). "However, tumor volume was consistently elevated in the CPT1A OE group." (PMID 34944922, 2021). "Carnitine palmitoyltransferase 1A (CPT1A)—involved in transferring long-chain FAs to the mitochondrial matrix—may have a special role in nutrient deprivation or other stress situations originating from the microenvironmental niche of tumours." (PMID 32899149, 2020). "Overexpression of CPT1A decreases confluency in MDA-MB231 cell line – As we had observed that the expression of the FAO signature is inversely correlated with proliferation in tumours, we investigated whether increased CPT1A expression altered the rate at which cultured cells achieved confluency." (PMID 30092766, 2018). "Thus, as both FBP1 and CPT1A are inhibitive of tumor growth and cell survival under stress, both genes display tumor suppressor phenotypes; though whether lipid deposition is a common mechanism of the effect remains to be investigated." (PMID 29176561, 2017). "Interestingly, high-fat feeding of the p48-Kras mouse model of pancreatic cancer accelerated tumor growth and increased energy expenditure and whole body fatty acid oxidation through increased gene expression of CPT1A, ACC, and AOX enzymes, key regulators of fatty acid oxidation." (PMID 25866768, 2015).